ABI3 (ABI family member 3)
Description:
May inhibit tumor metastasis (By similarity). In vitro, reduces cell motility.
Synonyms: Nesh; SSH3BP3
Tractability: PROTAC: ubiquitination databases record sites on it; its protein half-life has been measured.
Gene: Protein-coding gene on chromosome 17 (49,210,411 to 49,223,225, forward strand). Ensembl gene ENSG00000108798.
Subcellular location: Cytoplasm
Gene Ontology:
Molecular function: identical protein binding; protein binding; actin filament binding; signaling adaptor activity
Biological process: defense response to tumor cell; peptidyl-tyrosine phosphorylation; positive regulation of cellular senescence; regulation of cell migration; actin cytoskeleton organization; negative regulation of lamellipodium assembly; negative regulation of protein localization to plasma membrane; negative regulation of ruffle assembly; neuron migration; regulation of dendritic spine morphogenesis; regulation of postsynaptic density assembly; modification of postsynaptic actin cytoskeleton
Cellular component: cytoplasm; lamellipodium; membrane; SCAR complex; actin-based cell projection; dendritic shaft; dendritic spine; postsynaptic density; glutamatergic synapse; postsynapse
Genetic constraint (gnomAD): Loss-of-function variants: 24 observed, 30.33 expected, observed/expected ratio (o/e) 0.79, 90% interval 0.57 to 1.11. The upper end of that interval is the gene's LOEUF score, 1.11, which puts it in group 4 of 6, group 1 being the genes least tolerant of losing a copy. Missense variants: 481 observed, 458.35 expected, observed/expected ratio (o/e) 1.05, 90% interval 0.97 to 1.13. Synonymous variants: 220 observed, 198.05 expected, observed/expected ratio (o/e) 1.11, 90% interval 0.99 to 1.24.
Homologues: Orthologues: chimpanzee ABI3 (99% identical), macaque ABI3 (97% identical), dog ABI3 (89% identical), rabbit ABI3 (87% identical), mouse Abi3 (85% identical), rat Abi3 (85% identical), Drosophila melanogaster Abi (40% identical), Caenorhabditis elegans abi-1 (36% identical), zebrafish abi3b (29% identical). Paralogues in human: ABI2 (48% identical), ABI1 (47% identical).
Diseases named in the same sentence as ABI3 in open-access papers:
ABI3 is named in the same sentence as 40 diseases in open-access papers, as found by Europe PMC text mining. Sharing a sentence is not in itself a finding about the gene and the disease. The quoted sentences say what the papers report.
Alzheimer disease (18 papers, 2018 to 2025). A progressive, neurodegenerative disease characterized by loss of function and death of nerve cells in several areas of the brain leading to loss of cognitive function such as memory and language. "Studies also have verified that ABI3 contributes to the pathogenesis of age-associated Alzheimer’s disease (AD)." (PMID 38062164, 2024). "Human genetics studies of Alzheimer’s disease (AD) have identified the ABI3 gene as a candidate risk gene for AD." (PMID 36895556, 2023). "The S209F variant of Abelson Interactor Protein 3 (ABI3) increases risk for Alzheimer’s disease (AD), but little is known about its function in relation to AD pathogenesis." (PMID 35897046, 2022). "Alzheimer’s disease (AD) genetics studies have identified a coding variant within ABI3 gene that increases the risk of developing AD." (PMID 36620768, 2022). "Recently, large-scale human genetics studies identified a rare coding variant in the ABI3 gene that is associated with an increased risk of Alzheimer’s disease (AD)." (PMID 34731000, 2021). "Missense variants ABI3_rs616338-T and PLCG2_rs72824905-G were previously associated with elevated or reduced risk of Alzheimer’s disease (AD), respectively." (PMID 33092647, 2020). "Rare, missense variants ABI3_rs616338-T and PLCG2_rs72824905-G were associated with respectively higher (OR = 1.43) and lower (OR = 0.68) risk of Alzheimer’s disease (AD) in a large study comprised of 48,402 cases and 37,022 controls." (PMID 33092647, 2020). "Within our mouse innate immune network, we first confirmed the significance of several members of the network that were orthologues of established Alzheimer’s disease loci variants using the gene-level P-values, including genes such as Trem2 and Abi3." (PMID 32274467, 2019). "Rare coding variants in TREM2, PLCG2, and ABI3 were recently associated with the susceptibility to Alzheimer’s disease (AD) in Caucasians." (PMID 30705288, 2019). "Rare coding variants ABI3_rs616338-T and PLCG2_rs72824905-G were identified as risk or protective factors, respectively, for Alzheimer’s disease (AD)." (PMID 30326945, 2018). "The FN1+ MG subcluster exhibits high expression of the Alzheimer’s disease risk genes ABI3, CD33, and PTK2B, suggesting that this component of CSF microglia-like cells could emerge from a specific myeloid cell response to protein aggregates accumulating in the parenchyma during neurodegeneration." (PMID 39744938, 2025). "We also observed 3 additional DMRs annotated to ZFP57, ALLC, ABI3, and all of them have been described to be involved in Alzheimer’s disease (AD)." (PMID 38845005, 2024). "Recent genome-wide association studies have identified several Alzheimer’s disease (AD)-associated risk loci in genes selectively or preferentially expressed in microglia (e.g. TREM2, ABI3, PLCG2)." (PMID 32917267, 2020). "Rare nonsynonymous variants in ABI3 (p.Ser209Phe; rs616338-T) and PLCG2 (p.Pro522Arg; rs72824905-G) have recently been implicated in conferring risk and protection, respectively, for Alzheimer’s disease (AD)." (PMID 30326945, 2018). "Notably, two genes, ABI3 and PLCG2, that were identified subsequently as being associated with Alzheimer’s disease risk loci, were also present in this network." (PMID 32274467, 2019). "In addition, a panel of Alzheimer’s-disease relevant genes, which are consistently up-regulated in the transgenic CRND8 mouse brain over time, also reveals variable (Abi3 versus Plcg2)—and sometimes unexpected (Trem2)—responses to Aβ peptides in microglia." (PMID 34127518, 2021).
thyroid cancer (5 papers, 2011 to 2023). "Restoration of ABI3 expression in thyroid carcinoma cells by 5-aza-dC treatment confirmed a causal correlation between DNA hypermethylation and ABI3 silencing in thyroid cell lines." (PMID 27036019, 2016). "More extensive studies are needed to identify proteins that may interact with ABI3 in thyroid cells and, particularly, to identify the underlying mechanism by which ABI3 expression is lost in follicular cell-derived thyroid cancer and carcinoma cell lines." (PMID 27036019, 2016). "In this paper, we focus on the mechanism associated with ABI3 silencing in thyroid carcinomas." (PMID 27036019, 2016). "We also demonstrated that transcriptional silencing of ABI3 in thyroid cancer occurs via methylation of specific GpG sites located within the ABI3 promoter." (PMID 28978070, 2017). "Using proteomic array analysis, we showed that ABI3 modulated distinct cancer-related pathways in thyroid cancer cells." (PMID 28978070, 2017). "We previously reported that ABI3 (ABL-Interactor member 3) expression is lost in most thyroid carcinomas, compared to benign lesions and normal thyroid tissues." (PMID 28978070, 2017). "This study reveals a new region in the ABI3 promoter that show differential methylation patterns in benign and malignant thyroid tumors." (PMID 27036019, 2016). "We here demonstrated that ABI3 expression was restored in four thyroid carcinoma cells (FTC 238, FTC 236, FTC 133 and WRO) after treatment with demethylating agent 5-aza-dC." (PMID 27036019, 2016). "We previously reported that ABI3 expression is reduced or lost in follicular cell-derived thyroid carcinomas as compared to normal tissues and follicular thyroid adenomas (FTA)." (PMID 27036019, 2016). "We additionally show that 8 CpG sites located within the ABI3 promoter are hypermethylated in most thyroid carcinoma samples and the degree of methylation correlated with ABI3 expression." (PMID 27036019, 2016). "We further demonstrated that ectopic expression of ABI3 inhibited cell proliferation, invasion, migration and delayed cell cycle progression of thyroid carcinoma cell line in vitro." (PMID 27036019, 2016). "The present study investigated ABI3 expression in a large panel of benign and malignant thyroid tumors and explored a correlation between the expression of ABI3 and its potential partner ABI3-binding protein (ABI3BP)." (PMID 21223585, 2011). "As demonstrated by qPCR, ABI3 expression was reduced in a high percentage of thyroid carcinomas while it was expressed in most of benign lesions and normal thyroid (p≤0.001)." (PMID 21223585, 2011). "The suppression of TTF1 could favor the re-expression of the tumor suppressor ABI3, as previously published, thus supporting the cell death mechanism mediated by deacetylase inhibitors in thyroid cancer cells." (PMID 29561759, 2018). "In addition to its suppressive role in thyroid cancer, it has been demonstrated that ABI3 expression is frequently lost in invasive cancer cell lines." (PMID 28978070, 2017). "We previously reported that ABI3 expression was decreased in thyroid cancer tissues and that ectopic expression of ABI3 in a follicular thyroid carcinoma cell line delayed cell cycle progression and inhibited cell proliferation, invasion, migration and tumor formation in athymic mice." (PMID 27036019, 2016). "In this study we investigated the hypothesis that ABI3 is epigenetically silenced in thyroid carcinomas via DNA methylation." (PMID 27036019, 2016). "We identified a cancer-specific differentially methylated region located in the ABI3 promoter, which is hypermethylated in thyroid cell lines and thyroid carcinoma samples while is hypomethylated in the benign samples (FTA) and in a non-thyroid cell model (melanoma cells)." (PMID 27036019, 2016). "We found a decreased expression of ABI3 in thyroid carcinomas." (PMID 21223585, 2011).
thyroid cancer (continued). "Our hypothesis is that, similar to ABI3BP, ABI3 expression might be reduced in thyroid carcinomas and possibly plays a functional role in the pathogenesis and/or progression of thyroid tumors as well as other cancers." (PMID 21223585, 2011). "The results indicate that promoter methylation plays an important role in the down-regulation of ABI3 expression in thyroid cell lines and thyroid carcinoma tissues and explain, at least in part, why ABI3 silencing might occur in a cancer- and tissue-specific manner." (PMID 27036019, 2016). "We then evaluated the methylation status of CpG sites located at R1 region in two additional thyroid carcinoma cell lines (FTC 236 and FTC 133), which the expression of ABI3 was increased following treatment with 5-aza-dC." (PMID 27036019, 2016). "As most thyroid carcinomas did not express ABI3, the correlation among ABI3, WAVE2 and CYFIP1 was not performed in this set of samples." (PMID 28978070, 2017). "Here we demonstrated that when thyroid carcinoma cell lines, which express virtually no ABI3, were grown in the presence of demethylating agent 5-aza-dC, the expression of ABI3 was restored." (PMID 27036019, 2016). "To functionally explore this hypothesis we initially investigated the levels of ABI3 and NKX2-1 in 5-aza-dC treated and untreated thyroid carcinoma and melanoma cells lines." (PMID 27036019, 2016).
amyloid (4 papers, 2021 to 2023). "We demonstrated that Abi3 deficiency markedly increased soluble and insoluble Aβ levels and amyloid plaque load both in male and female mice." (PMID 34731000, 2021). "To determine the role of ABI3 at the early stage of amyloid pathology, we crossed Abi3 knock-out mice with the 5XFAD Aβ-amyloidosis mouse model and aged them until 4.5-month-old." (PMID 36895556, 2023). "Bulk RNAseq data reveals increased levels of ABI3 RNA relative to control cohorts in both the temporal cortex and cerebellum of human patients and in mouse models of amyloid and tau pathologies." (PMID 35897046, 2022). "Recently, we demonstrated that deletion of the Abi3 gene locus dramatically exacerbates AD neuropathology in a transgenic mouse model of amyloidosis." (PMID 36620768, 2022). "Therefore, we generated a 4.5-month-old cohort using the 5XFAD transgenic model to gain better insight into the role of Abi3 during Aβ-amyloidosis progression." (PMID 36895556, 2023). "Surprisingly, the Abi3-Gngt2−/− mice showed induction of the amyloid/AD-associated PIG network, even in the absence of Aβ (p < 0.01 relative to both WT and heterozygous mice)." (PMID 35897046, 2022). "Another study reported an increase in the number of IBA1-positive cells, although the total area covered by IBA1 staining was decreased in Abi3-/- mice without amyloid pathology." (PMID 36895556, 2023).
follicular thyroid carcinoma (4 papers, 2011 to 2023). "Previous reports have shown that ABI3 expression is lost in follicular thyroid carcinoma and its restoration significantly inhibits cell proliferation, invasion, migration and tumor formation, acting as a tumor suppressor gene." (PMID 37845004, 2023). "For functional analysis, a thyroid follicular carcinoma cell line (WRO) was permanently transfected with phCMV2 expressing the full-length HA-tagged ABI3 (HA-phCMV2-ABI3) or with the control vector (HA-phCMV2)." (PMID 28978070, 2017). "Down-regulation of these pathways, known as crucial to tumor growth and differentiation in different tumors subtypes, can explain, at least in part, the biological effects observed following forced expression of ABI3 in follicular thyroid carcinoma cells." (PMID 28978070, 2017). "The forced expression of ABI3 in two follicular thyroid carcinoma cell lines (WRO and FTC 133) markedly decreased the phosphorylation of AKT at both T308 and S473, as well as the phosphorylation of the downstream-targeted protein pGSK3β at S9 (P<0.05)." (PMID 28978070, 2017). "We previously reported that ABI3 expression is lost in follicular thyroid carcinomas and its restoration significantly inhibited cell growth, invasiveness, migration, and reduced tumor growth in vivo." (PMID 28978070, 2017). "We previously showed that ectopic expression of ABI3 in a follicular thyroid cancer cell line inhibited cell growth, invasiveness and migration in vitro, and reduced tumor growth in vivo." (PMID 28978070, 2017). "We also demonstrated that transcriptional silencing of ABI3 in follicular thyroid cancer cells and follicular thyroid tumors occurs via methylation of specific GpG sites located within the ABI3 promoter." (PMID 28978070, 2017). "We here show that treatment of four follicular thyroid carcinoma cell lines with 5-aza-dC induced demethylation of a specific region of the ABI3 promoter and restored ABI3 expression." (PMID 27036019, 2016). "The methylation degree of CpG sites located at R1 correlated negatively with ABI3 expression in thyroid follicular cancer cells (r = −0.8312 and P = 0.0053), perhaps characterizing a new cDMR." (PMID 27036019, 2016). "Remarkable, drug-induced hypomethylation of R1 correlated with the reestablishment of ABI3 expression in all follicular thyroid carcinoma cell lines." (PMID 27036019, 2016). "We confirmed that ABI3 was expressed in follicular carcinomas cells only when these specific CpG sites located at the promoter region of ABI3 (R1 region) were demethylated and NKX2-1 was present." (PMID 27036019, 2016). "We first demonstrated that ABI3 ectopic expression reduced cell transformation and suppressed proliferation of carcinoma cell lines, mainly in a follicular thyroid carcinoma cell line." (PMID 21223585, 2011). "Moreover, ABI3 re-expression in a human follicular thyroid carcinoma cell line significantly inhibited cell proliferation, invasion, and migration in vitro and reduced tumor growth in vivo." (PMID 28978070, 2017). "We here speculate whether decrease or absence of ABI3 expression is correlated with hypermethylation of the ABI3 in primary follicular thyroid carcinomas (FTC) tissues and in follicular thyroid carcinoma cell lines." (PMID 27036019, 2016). "The undetectable basal expression and high fold induction of ABI3 in the follicular thyroid carcinoma cell line could provide a potential explanation for the observed inhibitory effects of ABI3 on the cell proliferation." (PMID 21223585, 2011). "We previously demonstrated ABI3 is expressed in normal thyroid and follicular thyroid adenoma (FTA), while its expression is lost in most follicular thyroid carcinomas." (PMID 28978070, 2017).
colon carcinoma (3 papers, 2011 to 2023). "ABI3 expression is frequently reduced or lost in most colon cancer cell lines, and interestingly, there exists a positive correlation between ABI3 and ABI3BP expression in these carcinomas." (PMID 37768206, 2023). "We next explored the biological role of ABI3 in thyroid and colon carcinoma cells." (PMID 21223585, 2011). "To this end, we stably transfected ABI3 into a thyroid and a colon carcinoma cell lines." (PMID 21223585, 2011). "We next explored the biological effects of ABI3 ectopic expression in thyroid and colon carcinoma cell lines, in which its expression was reduced or absent." (PMID 21223585, 2011).
melanoma (3 papers, 2016 to 2024). A malignant, usually aggressive tumor composed of atypical, neoplastic melanocytes. "We observed that melanoma patients with high-ABI3 expression demonstrated better survival probability and higher response rates (57.14%) to anti-PD-1 therapy." (PMID 37942289, 2023). "We demonstrated ABI3 as a robust prognostic biomarker in melanomas, effectively predicting responses to anti-PD-1 immunotherapies." (PMID 37942289, 2023). "We also analyzed whether the transcription level of ABI3 is regulated by DNA methylation in a melanoma cell line (NPA)." (PMID 27036019, 2016). "Conversely, ectopic expression of NKX2-1 in melanoma cells lead to an increase in ABI3 expression." (PMID 27036019, 2016). "On the other hand, the 5-aza-dC treatment did not induce the transcription of ABI3 in a melanoma cell line." (PMID 27036019, 2016). "In melanoma cells, even though the CpG sites at this specific region were hypomethylated, ABI3 could not be detected, most likely because NKX2-1 was absent in these cells." (PMID 27036019, 2016).
tauopathy (3 papers, 2019 to 2025). Neurodegenerative disorders involving deposition of abnormal tau protein isoforms (tau proteins) in neurons and glial cells in the brain. "Overall, the effect of tauopathy on astrogliosis was most prominent in 6-month-old Abi3-Gngt2−/− mice." (PMID 35897046, 2022). "Because of the inherent dysfunctional immune milieu and early astrocytosis in the Abi3-Gngt2−/− mice, we decided to test how this would affect the development and progression of tauopathy." (PMID 35897046, 2022). "In APP transgenic TgCRND8 mice, loss of Abi3-Gngt2 results in a gene dose- and age-dependent reduction in Aβ deposition, but in Abi3-Gngt2−/− mice, AAV-mediated expression of a pro-aggregating form of human tau exacerbates tauopathy and astrocytosis." (PMID 39774290, 2025). "Additionally, in Abi3-Gngt2−/− mice, expression of a pro-aggregant form of human tau exacerbated tauopathy and astrocytosis." (PMID 35897046, 2022).